C3 (complement C3)
Diseases named in the same sentence as C3 in open-access papers (continued):
Sharing a sentence is not in itself a finding about the gene and the disease.
retinopathy (8 papers, 2010 to 2025). "Therefore, we investigated associations between C3 N-glycan profiles and albuminuria and retinopathy accompanying T1D, as well as glycosylation connection with other known T1D complication risk factors." (PMID 37293493, 2023). "Patients with retinopathy had lower hemoglobin, C3, and C4 levels, and higher ANA and Anti-dsDNA levels." (PMID 34593048, 2021). "Similar to previous reports, we found that patients with retinopathy have lower C3 and C4 concentrations, and have higher levels of ANA and Anti-dsDNA, findings which indicate an antibody-mediated retinal damage pathogenesis." (PMID 34593048, 2021). "While enhanced C3a signaling facilitates M1 polarization to exacerbate renal interstitial fibrosis, C3 gene deletion increased neovascularization in a mouse retinopathy model." (PMID 34150781, 2021). "Serum C3 and C4 levels were significantly lower in patients with retinopathy (55 ± 15 vs 85 ± 15, P = 0.001; 12 ± 10 vs 90 ± 18, P = 0.036, respectively)." (PMID 34593048, 2021). "C3a and C5a are inhibitory effectors of pathological hypoxia-driven retinal neovascularization in the C3−/− or C5aR−/− mouse retinopathy model." (PMID 30841875, 2019). "Hence, we compared measured C3 N-glycome profiles between different stages of T1D complications (albuminuria and retinopathy divided into three categories)." (PMID 37293493, 2023). "Additionally, the most unprocessed C3 glycoform, C3.Asn939-N2H10, significantly increased in non-proliferative retinopathy and across albuminuria stages." (PMID 37293493, 2023).
genetic disorders (4 papers, 2012 to 2023). "CFH was the first protein to be associated with genetic disease, followed by CFI and MCP, and then by C3/C3b." (PMID 25188723, 2014). "The relative health of the heterozygous mice (C3KI/WT) despite markedly increased complement turnover also offers the potential to investigate how C3 activity shapes the progression of other complex genetic disorders, such as rheumatic and neurological conditions, including AMD." (PMID 30714990, 2019). "In this study, we found that in 45 children diagnosed with aHUS, genetic disorders in complement-regulating genes encoding CFH, CFI, MCP, CFB, C3, and THBD, as well as the presence of αFH with or without a homozygous deletion in CFHR1/3, are linked with clinical presentation, treatment, and outcome." (PMID 22410797, 2012).
heart disease (4 papers, 2020 to 2025). "Previous immunofluorescence studies found C3 deposition in the pericardium, suggesting complement system involvement in the pathogenesis of cardiac disease related to SLE." (PMID 41155225, 2025). "While C3 deficiency does not cause heart disease itself, its absence can worsen outcomes in those who develop cardiac issues, suggesting C3 plays a role in cardiac repair and inflammatory response after injury." (PMID 41155225, 2025).
psychiatric disorder (4 papers, 2015 to 2022). A disorder characterized by behavioral and/or psychological abnormalities, often accompanied by physical symptoms. "Previous studies have indicated that the activity of complement components (including complement component C3) is tightly controlled in the brain, and deregulation of complement has been found to be involved in psychiatric disorders such as SCZ." (PMID 27377754, 2016).
adenocarcinoma (3 papers, 2020 to 2024). A common cancer characterized by the presence of malignant glandular cells. "We then selected CPs with enrichment scores of less than -80 in both adenocarcinoma cell lines as potentially capable of reversing the C3 aberrant gene expression." (PMID 32855362, 2020).
disorders of the central nervous system (3 papers, 2010 to 2024). "The C3-C3aR pathway is implicated in a variety of central nervous system diseases via mediation of the neuron–glia network function containing synapse elimination and refinement, cognitive function, dendritic morphology, neuroinflammation and neurodegeneration." (PMID 36831807, 2023).
respiratory disease (3 papers, 2018 to 2020). "In a SARS-CoV-infected mice study, it was reported that complement activation results in immune-mediated damage in the lung of C3 deficient mice, which suggested that inhibition of the complement pathway might be an effective therapeutic strategy to inhibit coronavirus-mediated respiratory diseases." (PMID 32566414, 2020). "Together, these data indicate that despite the lack of weight loss in C3–/– mice, the absence of the complement pathway did not alter host control of viral replication or completely abolish respiratory disease following SARS-CoV MA15 infection." (PMID 30301856, 2018).
vasculopathy (3 papers, 2022 to 2025). "Factors such as age, diastolic blood pressure, and circulating complement C3 levels have been associated with the progression of vasculopathy, supporting the hypothesis that the complement system may contribute to the pathogenesis of MMD." (PMID 41154172, 2025).
brain diseases (2 papers, 2016 to 2023). "Altogether these results suggest that CCAAT/enhancer-binding protein β could regulate brain disorders, in which excitotoxic and inflammatory processes are involved, at least in part through the direct regulation of C3." (PMID 27769255, 2016).
hematological cancer (2 papers, 2017 to 2020). "In comparison with patients who developed solid cancer, those who developed hematological cancer had a higher frequency at diagnosis of cryoglobulins (p = 0.002), low C3 levels (p = 0.018), high ESSDAI score (p = 0.001), and high DAS (p < 0.001)." (PMID 28416003, 2017).
peripheral neuropathy (2 papers, 2021 to 2025). A disorder affecting the peripheral nervous system. "As another part of the innate immune system, the complement system was linked via complement component 3 (C3) activation to paclitaxel-induced peripheral neuropathy." (PMID 34678925, 2021).
urinary disease (2 papers, 2021 to 2022). "C3 and PLG were selected as hub proteins associated with renal and urological disease." (PMID 36211816, 2022).
congenital disorders of metabolism (1 paper, 2024). "SRGs at the PY20 stage are enriched in complement C3 and C4 levels, congenital disorders of metabolism, and the stress-induced intrinsic apoptotic signaling pathway." (PMID 39183748, 2024).
C3 also shares sentences with these, for which no sentence is quoted: glomerulopathy (17 papers); Glomerular sclerosis (14); focal segmental glomerulosclerosis (10); connective tissue disease (8); purpura (8); Hepatitis (6); idiopathic pulmonary fibrosis (6); Immune Complex-Mediated Membranoproliferative glomerulonephritis (5); acute myocardial infarction (4); cognitive disorder (4); Disseminated intravascular coagulation (4); E. coli infection (4); metastatic melanoma (4); pertussis (4); polycystic ovary syndrome (4); ulcerative colitis (4); acne (3); brain injury (3); breast tumors (3); cardiac arrest (3); diabetic neuropathy (3); glomerular basement membrane disease (3); Goodpasture syndrome (3); head and neck squamous cell carcinoma (3); immunodeficiency (3); lysosomal storage disease (3); Multiple Organ Failure (3); neurodevelopmental disorder (3); non-Hodgkin lymphoma (3); pemphigus vulgaris (3).
A further 221 diseases each share a sentence with C3 in 3 papers or fewer.